GAST (gastrin)
Diseases named in the same sentence as GAST in open-access papers (continued):
Sharing a sentence is not in itself a finding about the gene and the disease.
GAST also shares sentences with these, for which no sentence is quoted: iron deficiency (4 papers); carcinoid syndrome (3); Acquired immune deficiency syndrome (2); alcoholism (2); Anorexia (2); autoimmune thyroid disease (2); erectile dysfunction (2); gastric carcinoid tumors (2); hypertensive nephropathy (2); hypertrophy (2); Infertility (2); Lung Disease (2); multiple endocrine neoplasia (2); parathyroid hyperplasia (2); small cell lung carcinoma (2); squamous cell carcinoma (2); uremia (2); Alzheimer disease (1); amenorrhea (1); amyotrophic lateral sclerosis (1); anxiety disorder (1); autoimmune enteropathy (1); Barrett’s oesophagus (1); bleeding (1); brain disorder (1); bulimia (1); Chagas disease (1); cholelithiasis (1); cholestasis (1); Chronic diarrhea (1).
A further 63 diseases each share a sentence with GAST in 1 paper.